INS (insulin)
Diseases named in the same sentence as INS in open-access papers (continued):
Sharing a sentence is not in itself a finding about the gene and the disease.
Insulin resistance (continued). "We believe that physiological insulin resistance in our healthy controls was compensated by their β-cells insulin secretion at sufficient level to maintain normoglycemia, while in the PCH the capacity of β-cells insulin secretion began to be insufficient." (PMID 32405763, 2021). "Insulin resistance is characterized by a decreased responsiveness of insulin sensitivity and supraphysiological levels of insulin." (PMID 33935964, 2021). "Chronic exposure of β-cells and insulin target tissues to hyperglycemia leads to the deterioration of β-cell function and aggravation of insulin resistance." (PMID 33807522, 2021). "While facing the challenges of environmental hazards and insulin resistance, the gut microbiota can ride winds (environmental hazards) and break waves (insulin resistance)." (PMID 35111696, 2021). "It has also been proven to reduce hypoglycemia and insulin resistance problems, which seem to be the main adverse effects of using conventional insulin regularly." (PMID 34540446, 2021). "In this line, it is well known that BCSs’ risk of recurrence is increased in women who have attributes of the insulin resistance conditions, such as central obesity, high endogenous insulin levels, clinical metabolic syndrome and physical inactivity." (PMID 34204528, 2021). "As reported that supplementation of vitamin D ameliorated insulin resistance in patients with T2DM, it is thought that vitamin D deficiency results in a decrease of insulin sensitivity." (PMID 35223754, 2021). "Extracted DNJ appreciably decreased blood glucose and insulin levels, reversed insulin resistance, and enhanced serum lipid levels and in high fat diet-induced (HFD) diabetic Kunming mice." (PMID 34220247, 2021). "Excess body iron appears to be associated with adverse outcomes, insulin resistance, and accelerated disease progression in NAFLD, and iron depletion upon phlebotomy improved insulin sensitivity in these patients." (PMID 34067164, 2021). "Insulin resistance usually refers to a clinicopathological condition characterized by an impaired ability of insulin to stimulate glucose uptake and by glucose intolerance." (PMID 34053175, 2021). "Both oxidative stress and inflammation interfere with insulin signaling, leading to insulin resistance, DM, and related complications, and these processes are considered to be important components of the pathogenesis of DM." (PMID 33995040, 2021). "Xylitol infusion during insulin clamp studies in normal rats prevented fatty-acid-induced insulin resistance, with favourable effects on glycogen synthesis and insulin-mediated glucose uptake." (PMID 32767274, 2021). "As expected, the rats in the MC group had a significantly higher concentration of INS than those in the NC group, revealing that obese rats had severe insulin resistance." (PMID 33585429, 2021). "Inflammation can cause insulin resistance through Ser phosphorylation of insulin receptor substrate (IRS)-1, which inhibits insulin signaling." (PMID 34970150, 2021). "We selected RCTs that evaluated the effects of coffee consumption for seven days or more on insulin sensitivity or resistance using surrogate indices (homeostasis model assessment for insulin resistance (HOMA-IR) and Matsuda index)." (PMID 34836231, 2021). "For example, insulin resistance increases circulating free fatty acid (FFA) levels by reducing insulin-mediated suppression of lipolysis in the visceral adipose tissue compartment." (PMID 34113839, 2021). "Insulin therapy normalized Leptin and adiponectin receptor levels in these patients, which had prevented insulin resistance and effectively controlled the appetite and weight of obese patients." (PMID 34904015, 2021). "Recent studies have found that verapamil can inhibit the expression of TXNIP in islet P cells, improve islet P cell function, promote insulin synthesis and release, and improve insulin resistance and glucose metabolism disorder in diabetic mice." (PMID 34699301, 2021).
Insulin resistance (continued). "A marked increase in the plasma total cholesterol, triglycerides, LDL, insulin, and the homeostasis assessment of insulin resistance index (HOMA index); a decrease in HDL; and impaired kidney and liver function were shown in HFV rats." (PMID 33920678, 2021). "Insulin resistance has downstream effects on insulin signaling (e.g., IGF-1), adipokines (including adiponectin), and circulating pro-inflammatory cytokines that promote tumorigenesis." (PMID 34960058, 2021). "UTXKO mice also displayed glucose intolerance and insulin resistance as assessed by glucose and insulin tolerance tests (GTT and ITT, respectively)." (PMID 34824202, 2021). "Under conditions of insulin resistance, abnormally high levels of insulin are required to metabolize glucose and inhibit hepatic glucose production effectively due to reduced insulin sensitivity in peripheral tissues." (PMID 34083664, 2021). "Two subgroups (low = UIC < 100 μg/L and normal = UIC ≥ 100 μg/L) were compared for markers of IR, including fasting plasma glucose (FPG) and insulin, homeostatic model assessment of insulin resistance (HOMA-IR), and glycated hemoglobin (HbA1C)." (PMID 34960073, 2021). "The classical paradigm maintains that insulin resistance is the primary defect of T2D, followed by ‘compensatory’ increase in beta cells insulin production." (PMID 34659123, 2021). "Leptin decreases fat accumulation in the liver and generally functions to improve insulin sensitivity, but promotes insulin resistance during leptin resistance states." (PMID 36994336, 2021). "As a result, suppressing FOXO1 signalling can protect mice from HFD-induced insulin resistance by increasing insulin sensing regulator PPARγ." (PMID 34803738, 2021). "It has been established that PPARγ phosphorylation at Ser273 promotes insulin resistance in obese and diabetic mice, and classical PPARγ ligands such as TZDs inhibit Ser273 phosphorylation to improve insulin sensitivity." (PMID 34526909, 2021). "Excess adiposity causes insulin resistance, which in turn leads to an elevated levels of bioactive insulin-like growth factor-1 (IGF-1); both insulin and IGF-1 can increase proliferation and reduce apoptosis in sensitive cells." (PMID 34051796, 2021). "WAT insulin resistance can be attributed to a proximal defect in insulin signaling at the level of the Insr, which ultimately impacts the regulation of key lipolytic enzymes." (PMID 33411692, 2021). "Insulin resistance (IR) is a condition which refers to individuals whose cells and tissues become insensitive to the peptide hormone, insulin." (PMID 34681797, 2021). "When the cells were exposed to TNF-α for a sufficiently long time (18 h) to induce insulin resistance, the insulin-stimulated uptake of glucose was downregulated by 75% (bar 3 vs. 2, p < 0.05)." (PMID 34680177, 2021). "Compared with control group, 7.8 nM insulin induced insulin resistance and inhibited the absorption of glucose in HepG2 cells." (PMID 33681196, 2021). "Insulin resistance is defined as reduced tissue responsiveness to the physiological action of insulin." (PMID 34070553, 2021). "Peripheral insulin resistance and elevated plasma glucose and insulin levels are correlated with TNF-alpha concentration prior to the onset of T2DM." (PMID 34725640, 2021). "The altered nuclear-to-cytoplasmic ratio (N:C) of forkhead box O1 (FOXO1) in hyperglycemic MPCCs relative to normoglycemic MPCCs also implied abnormal influence of insulin on translocation of FOXO1 as seen in insulin-resistance patients." (PMID 34631680, 2021). "Chronic hyperinsulinemia, induced by insulin resistance, directly activates stellate cells, Moreover, this hyperinsulinemia disrupts insulin signaling and induces lipid accumulation in the skeletal muscles and liver." (PMID 34944764, 2021). "Acute inhibition (for 1 h) increased insulin signaling and glucose uptake, while chronic inhibition (for 24–48 h) induced insulin resistance and impaired insulin-mediated glucose uptake." (PMID 34689241, 2021).
Insulin resistance (continued). "On the other hand, the effect of barberry extract on insulin level and insulin resistance index (HOMA-IR) has been different between the studies." (PMID 34285701, 2021). "The time of peak serum glucose concentrations was delayed in all groups, especially in the control group, suggesting that all rats had insulin resistance and lower insulin secretion, and BC intake partially improved the delay of peak glucose." (PMID 34068659, 2021). "Insulin resistance (IRES) is a pathophysiological condition characterized by the reduced response to insulin of several tissues, including myocardial and skeletal muscle." (PMID 33467677, 2021). "These various data indicate that ADMSCs can promote the recovery of insulin resistance and significantly restore insulin sensitivity in mice." (PMID 34722505, 2021). "Insulin resistance indicates a reduced function of insulin in target tissues, such as the liver, muscles, and adipose tissue." (PMID 34489627, 2021). "For example, age-related mitochondrial dysfunction raises the level of ROS release from mitochondria, which induces phosphorylation of serine in IRS proteins and disturbs insulin signaling, resulting in insulin resistance." (PMID 35010981, 2021). "These bacteria provide energy for intestinal L cells to secrete GLP-1 or directly induce GLP-1 secretion to stimulate insulin secretion and improve the sensitivity of peripheral tissue to insulin to ameliorate insulin resistance." (PMID 34686199, 2021). "In both impaired glucose tolerance (prediabetes) and T2D, insulin resistance at the hepatic level and peripheral tissues occurs due to impaired insulin signaling and inappropriate hyperglucagonemia." (PMID 34882233, 2021). "Insulin signaling in the brain has become an important issue because brain insulin resistance appears to be an early and common feature of many neurodegenerative diseases." (PMID 34226528, 2021). "The Snx5 gene is located on chromosome 20p, a susceptibility quantitative trait locus for high fasting plasma insulin levels and insulin resistance." (PMID 33477364, 2021). "During pregnancy, the insulin requirement increases with reference to the physiological increase in insulin resistance, and CHO/IR decreases." (PMID 33732212, 2021). "As a result, insulin negatively regulates Aqp9 transcription, which explains why patients with insulin resistance are more likely to develop fatty liver disease, which can lead to CLI." (PMID 34659635, 2021). "She had insulin resistance, as assessed by very high fasting insulin levels (284 pmol/L), which increased over time." (PMID 34342583, 2021). "Epac2A seems to play a role in potentiation of GSIS under conditions of increased demand for insulin, e.g., in insulin resistance, such as during obesity." (PMID 34359828, 2021). "This mixed presentation induces obesity and insulin resistance, which leads to poor glycemic control and an increase in the amount of required daily insulin." (PMID 33409743, 2021). "Multiple studies have suggested that IL-6 leads to insulin resistance and promotes muscle atrophy, as skeletal muscle is the main tissue in which insulin stimulates glucose uptake." (PMID 34863141, 2021). "The increased expression of the VEGF gene was associated with insulin resistance, and that the neutralization of the VEGF gene resulted in improvement in insulin sensitivity in the liver and in fat tissues." (PMID 34889890, 2021). "On the other hand, IGT seems to be mainly determined by impaired insulin secretion (β-cell dysfunction) in relation to glycemia and the degree of insulin resistance." (PMID 33939909, 2021). "RAGE pathway is activated in conditions of de-regulated IGF/Insulin signaling and participates to the establishment of low-grade chronic inflammation and insulin resistance." (PMID 33557316, 2021). "Elevated FPG during pregnancy suggests insulin resistance, while insulin requirement indicates an impaired β-cell function." (PMID 33021758, 2021).
Insulin resistance (continued). "Increasing FFAs induces pancreatic insulin secretion, resulting in compensatory hyperinsulinemia and exacerbating insulin resistance." (PMID 33937238, 2021). "The disruption of the cephalic response increases caloric intake, increased caloric intake leads to increased adiposity and insulin resistance, thus requiring increased insulin secretion from beta cells." (PMID 33868167, 2021). "Except for expected higher insulin and Homeostatic Model Assessment for Insulin Resistance in IR subjects, the IS and IR subjects were comparable in their acute insulin response to glucose (AIRg), disposition indexes, and fasting plasma biochemistries." (PMID 34369385, 2021). "Insulin resistance and insufficient insulin secretion are well-recognized contributors to type 2 diabetes." (PMID 34206745, 2021). "Palmitate, a saturated fatty acid, has been found to induce insulin resistance through downregulation of the insulin-stimulated phosphorylation of Akt." (PMID 33799458, 2021). "Animal experiments revealed that injection of human SP at a concentration that increases SP concentration in diabetic patients inhibited insulin transduction in normal mice and induced hyperglycemia or insulin resistance." (PMID 33917105, 2021). "In contrast to most changed metabolites in peripheral insulin resistance, glycerophosphorylcholine had a higher abundance in the non-insulin resistant group." (PMID 33924347, 2021). "This study demonstrated that increasing exogenous insulin supply, which indirectly refers to insulin resistance, improves cognitive function in individuals with poorly controlled diabetes (HbA1c ≥ 9%)." (PMID 34577866, 2021). "Its activity involves the ability of reducing serum triglyceride clearance and improving insulin resistance through the regulation of hepatic and peripheral insulin sensitivity by yet unclear mechanisms." (PMID 33067796, 2021). "Compared with CD mice, HFD mice presented a relatively intact insulin-induced hypoglycemic response at week 4, whereas overt insulin resistance was only detectable after 8 weeks of diet treatment." (PMID 33817571, 2021). "Although enough insulin is produced to thwart a T2D diagnosis, prediabetes is characterized by exposure to abnormally high levels of insulin for years, which results in insulin resistance and, in turn, impaired fasting glucose." (PMID 33679574, 2021). "Given that SOCS proteins inhibit insulin/IGF-1 signaling, they are able to elicit insulin resistance, a condition which is known to be associated with aging." (PMID 34476533, 2021). "The involvement of RET oncogene in the same pathway of insulin signaling explains its role in the molecular pathogenesis of insulin resistance." (PMID 34360895, 2021). "An increase in fasting insulin levels and insulin resistance was hampered in individuals receiving carnosine supplementation." (PMID 34203479, 2021). "Metformin (1,1-Metformin Hydrochloride, Met) is considered an insulin sensitizer and can reduce insulin resistance by restoring insulin sensitivity." (PMID 33441838, 2021). "Primary hepatocytes were induced by hypochlorous acid (HClO) and insulin to form insulin resistance (IR)." (PMID 35096302, 2021). "5-HT3 receptors are required for glucose-induced insulin secretion and this is more important in mice fed high fat diets where an obesity induced insulin-resistant state is developed and in pregnant mice also suffering insulin resistance." (PMID 34769340, 2021). "Twelve studies assessing the influence of PD on carbohydrate metabolism, i.e., fasting plasma (fP) glucose (mmol/L), fP insulin (mmol/L), homeostasis model assessment of insulin resistance (HOMA-IR), and glycated hemoglobin (HbA1c) (%), were analyzed." (PMID 33801152, 2021). "For example, pharmacological elevation of adiponectin levels in obese mice protected from hyperglycemia, glucose intolerance, and insulin resistance as well as increasing insulin sensitivity." (PMID 34211985, 2021).
Insulin resistance (continued). "Inflammatory pathway activation has been observed in all classical insulin target tissues, indicating the key role of inflammation in driving the pathogenesis of systemic insulin resistance." (PMID 33717095, 2021). "When insulin resistance appears, insulin levels are elevated, and the resulting increase can be reflected by the detection of insulin content." (PMID 34976408, 2021). "Excessive intramyocellular lipid (IMCL) accumulation is a primary cause of skeletal muscle insulin resistance, especially in older adults, and interventions that reduce IMCL contents are important to improve insulin sensitivity." (PMID 34158031, 2021). "The aqueous extract of Cinnamon is known for insulin-regulation and glucose utilization via enhancing the insulin signaling pathway and preventing high-fructose diet-induced insulin resistance." (PMID 33435558, 2021). "Fasting plasma glucose (FPG), insulin, homeostasis model of assessment-estimated insulin resistance (HOMA-IR), quantitative insulin sensitivity check index (QUIKI), triglyceride (TG) were the primary outcomes." (PMID 33865313, 2021). "The intergenerational transmission of developmentally programmed insulin resistance is determined by the relative insulin sensitivity of the mother during pregnancy and/or lactation." (PMID 34209784, 2021). "Cardiac insulin resistance is mainly manifested by impaired cardiac insulin signaling and insulin-stimulated glucose metabolism." (PMID 34831481, 2021). "Finucane and Davenport argue that the state of insulin resistance and elevated insulin levels that are driving increased ACE2 expression in lung epithelial cells are responsible, at least in part, for aggravating disease severity." (PMID 34680053, 2021). "Exclusion of the proximal small intestine reduces the secretion of upper gastrointestinal factors such as anti-incretins, which are assumed to suppress insulin secretion or promote insulin resistance." (PMID 33914241, 2021). "In order to increase circulating insulin levels, the insulin homeostatic system responds to insulin resistance by increasing insulin secretion and reducing insulin clearance." (PMID 34206745, 2021). "Insulin resistance is defined as failure of insulin-target tissues to respond to insulin stimulation." (PMID 34745416, 2021). "Based on this evidence, researchers investigated the effects of myo-ins and d-chiro-ins administration in patients with insulin-related pathologies, like diabetes or insulin resistance." (PMID 34070701, 2021). "In conclusion, our study results suggest that although there is no exact link between laminin and non-alcoholic hepatosteatosis serum laminin levels are lower in patients with insulin resistance possibly by regulating the insulin effect through integrins." (PMID 34092237, 2021). "Type 2 diabetes (T2D) is a worldwide prevalent metabolic disorder defined by high blood glucose levels due to insulin resistance (IR) and impaired insulin secretion." (PMID 34884651, 2021). "It is known that patients who require >1 unit/kg/day of insulin are considered to have insulin resistance." (PMID 34577866, 2021). "Clustering analyses identified three unique phenotypic groups, where levels of insulin resistance, defined by insulin clamps, differed significantly between the groups." (PMID 34426590, 2021). "We will also study the effect of the intervention on the 6-month change in the following exploratory outcomes: fasting insulin and homeostasis model assessment of insulin resistance (HOMA-IR), diastolic BP, waist circumference, and 10-year estimated CVD risk." (PMID 33522954, 2021). "Insulin resistance promotes compensatory insulin secretion and insulin by itself has different effects on the kidney." (PMID 33928108, 2021). "We then exposed Igf2βKO and littermate control mice to several models of increased metabolic demand leading to insulin resistance and therefore need for increased insulin release." (PMID 33833312, 2021).